DEFB134 (defensin beta 134)
Description:
Has antibacterial activity.
Tractability: Antibody: UniProt places it where antibodies can reach, with high confidence; UniProt predicts a signal peptide or a membrane-spanning region; its Gene Ontology location is reachable by antibodies, with medium confidence.
Gene: Protein-coding gene on chromosome 8 (11,993,174 to 12,000,752, reverse strand). Ensembl gene ENSG00000205882.
Subcellular location: Secreted
Pathways (Reactome):
Immune System: Beta defensins; Defensins
Gene Ontology:
Biological process: innate immune response
Cellular component: extracellular region
Genetic constraint (gnomAD): Loss-of-function variants: 7 observed, 7.53 expected, observed/expected ratio (o/e) 0.93, 90% interval 0.53 to 1.67. That is too few expected variants to judge how well the gene tolerates losing a copy. Missense variants: 105 observed, 78.83 expected, observed/expected ratio (o/e) 1.33, 90% interval 1.14 to 1.57. Synonymous variants: 33 observed, 26.69 expected, observed/expected ratio (o/e) 1.24, 90% interval 0.94 to 1.65.
Homologues: Orthologues: chimpanzee DEFB134 (100% identical), macaque DEFB134 (91% identical), mouse Defb22 (27% identical), rat Defb22 (23% identical). Paralogues in human: DEFB121 (33% identical), DEFB118 (30% identical), DEFB123 (30% identical), DEFB116 (29% identical), DEFB128 (29% identical), DEFB132 (29% identical), DEFB115 (27% identical), DEFB119 (27% identical), DEFB124 (27% identical), DEFB125 (26% identical), DEFB127 (26% identical), DEFB129 (26% identical), and 7 more.
Diseases named in the same sentence as DEFB134 in open-access papers:
DEFB134 is named in the same sentence as 2 diseases in open-access papers, as found by Europe PMC text mining. Sharing a sentence is not in itself a finding about the gene and the disease. The quoted sentences say what the papers report.
atrioventricular septal defect (1 paper, 2024). "The geneDEFB134, defensin beta 134, has been associated with an atrioventricular septal defect in fetuses, and this association has been established in cases involving a complete deletion of DEFB134." (PMID 38473795, 2024).
cardiovascular diseases (1 paper, 2024). "To date, no reports in the scientific literature have linked the DEFB134 gene to cardiovascular diseases in adults." (PMID 38473795, 2024).